C12orf76 (chromosome 12 open reading frame 76)
Synonyms: FLJ40142
Gene: Protein-coding gene on chromosome 12 (110,027,028 to 110,073,636, reverse strand). Ensembl gene ENSG00000174456.
Genetic constraint (gnomAD): Loss-of-function variants: 3 observed, 2.5 expected, observed/expected ratio (o/e) 1.2, 90% interval 0.49 to 1.9. That is too few expected variants to judge how well the gene tolerates losing a copy. Missense variants: 96 observed, 81.9 expected, observed/expected ratio (o/e) 1.17, 90% interval 0.99 to 1.39. Synonymous variants: 56 observed, 36.88 expected, observed/expected ratio (o/e) 1.52, 90% interval 1.22 to 1.86.
Homologues: Orthologues: pig C12orf76 (88% identical), guinea pig C12orf76 (81% identical), rat C12h12orf76 (78% identical), rabbit C12orf76 (71% identical).
Diseases named in the same sentence as C12orf76 in open-access papers:
C12orf76 is named in the same sentence as 2 diseases in open-access papers, as found by Europe PMC text mining. Sharing a sentence is not in itself a finding about the gene and the disease. The quoted sentences say what the papers report.
migraine with aura (1 paper, 2025). A migraine disorder characterized by episodes that are preceded by focal neurological symptoms. "At the brain‐tissue level, we further validated hub gene associations: in migraine, SERPINC1, ZKSCAN8P1, C12orf76, and PAM were significant across brain regions; in migraine with aura, SERPINC1, ALMS1, ZKSCAN8P1, PAM, and NCF2 were significant." (PMID 41261954, 2025). "Overall, C12orf76 remains poorly characterized but shows brain expression and predicted membrane localization with 12q24 regional signals, making it a plausible yet provisional neurovascular/immune interface for migraine." (PMID 41261954, 2025). "SMR and INTACT confirmed the validity of BLM, C12orf76, GPATCH4, PAM, SERPINC1 for migraine, and ALMS1, GPATCH4, NCF2, SLC12A1, ZKSCAN8P1 for migraine with aura." (PMID 41261954, 2025). "The results of the SMR, colocalization, and INTACT sensitivity analyses provided further validation of BLM, C12orf76, GPATCH4, PAM, SERPINC1 as contraindicated drugs’ target genes for migraine, and ALMS1, GPATCH4, NCF2, SLC12A1, ZKSCAN8P1 for migraine with aura." (PMID 41261954, 2025).
C12orf76 also shares sentences with these, for which no sentence is quoted: Hypertension (1 paper).